USP14 (ubiquitin specific peptidase 14)
Diseases named in the same sentence as USP14 in open-access papers (continued):
Sharing a sentence is not in itself a finding about the gene and the disease.
tumor (continued). "The significant clinical relevance of USP14, BAG4, and PRKN are proved in tumor tissues." (PMID 40316942, 2025). "Due to their involvement in tumor metastasis and progression, ABCF1 and USP14 were discovered." (PMID 39968078, 2025). "Conversely, the overexpression of exogenous USP14 in OSCC cells significantly enhanced cell proliferation, colony formation, and migration—all features that promoted the malignant biological behaviors of tumor cells." (PMID 38388430, 2024). "The results showed that both PFKL and USP14 protein expression increased in tumor tissues compared to that in their matched adjacent non-cancerous tissues, which exhibited consistent trends." (PMID 38388430, 2024). "In addition, USP14 is known to regulate the PI3K/AKT pathway and affect the malignant phenotype of tumor cells." (PMID 37046655, 2023). "Moreover, USP14 expression is induced by TNF-α, forming a feedback loop with JNK and leading to tumor amplification." (PMID 36693850, 2023). "We reasoned that the reduced levels of USP14 in ML1 cells could afford an advantage for using USP14 inhibitors, such as IU1 as the tumor cells may be more sensitive to its action compared with control cells." (PMID 37711852, 2023). "In addition, depletion of USP14 led to proteasome-dependent degradation of TAZ and ultimately arrested PDAC tumour growth and liver metastasis." (PMID 35906484, 2023). "USP14 expression in HCC is significantly elevated in tumor tissues and promotes tumor progression." (PMID 35203285, 2022). "Collectively, these data demonstrated that USP14 promoted HCC proliferation and tumor growth." (PMID 34420039, 2021). "The restoration of USP14-WT, in contrast to USP14 C114A, rescued GSC cell proliferation, sphere-forming frequency, and radioresistance, as well as reacquired the ability for intracranial tumor xenograft growth, ultimately diminishing the overall survival of tumor-bearing hosts." (PMID 39990235, 2025). "Although the overexpression of USP14 alone was insufficient to polarize macrophages to an M2 phenotype, inhibiting USP14 with IU1 in tumor-bearing mice disrupted the suppressive activity of pro-tumor macrophages and effectively remodeled the immune microenvironment characteristics." (PMID 39944823, 2025). "Moreover, in HCC patients not treated with lenvatinib, the expression of USP14, as indicated by immunohistochemistry, was higher in tumor samples than in normal samples." (PMID 38993552, 2024). "However, the regulatory effect of USP14 on ferroptosis in DDP-resistant tumor cells has not been studied." (PMID 38819674, 2024). "We demonstrated that USP14 specifically interacts with PFKL and enhances its stability through deubiquitination in OSCC cells, which in turn enhances PFKL-mediated glycolytic metabolism, ultimately promoting the proliferation, migration, and tumorigenesis of tumor cells." (PMID 38388430, 2024). "Collectively, we uncovered that hyperactive USP14 contributed to HNSCC tumor growth and lung metastasis by reinforcing HSF1-depedent HSP activation, and our findings provided the insight that targeting USP14 could be a promising prognostic and therapeutic strategy for HSNCC." (PMID 37686660, 2023). "In addition, USP14 deubiquitinates and increases the stability of C-X-C Motif chemokine receptor 4 (CXCR4), which is highly expressed in tumors and plays an important role in tumor immune suppression." (PMID 36163134, 2022). "The result from GSE62165 and GSE21501 indicated that the expression levels of six-USPs were not related to tumor location (N = 118) and tumor size (N = 98), while GSE21501 data showed that USP10 and USP14 were robustly associated with lymphatic metastasis (N = 101)." (PMID 36582601, 2022).
tumor (continued). "To further examine the biological function of USP14 in cell growth in vivo, we conducted subcutaneous xenograft tumor experiments in nonobese diabetic/severe combined immunodeficiency mice to detect the effect of USP14 depletion on cell growth in EC-derived cells." (PMID 36423684, 2022). "Moreover, the univariate analysis showed that differentiation (P = 0.036), tumor size (P = 0.016), lymph node metastasis (P < 0.001), TNM stage (P < 0.001), invasion into serous membrane (P = 0.016), and USP14 overexpression (P = 0.002) were correlated with DFS, respectively." (PMID 30296012, 2018). "In this study, we further demonstrated that aberrantly overexpressed USP14 was also closely related to adverse clinicopathological features and poor prognosis in patients with OSCC, so we hypothesized that USP14 might act as a tumor-promoting factor during the progression of OSCC." (PMID 38388430, 2024). "While USP14 overexpression alone is not enough to polarize macrophages, inhibiting USP14 with IU1 can reshape the tumor microenvironment, underscoring SIRT1’s key role in the “cold tumor” phenotype." (PMID 40567502, 2025). "Recently it was also established that targeted inhibition of USP14 and UCHL5 with the novel small-molecule proteasome inhibitor b-AP15 induced proteotoxic stress and apoptosis in tumor cells of WM, without affecting proteolytic activity of the 20S proteasome." (PMID 32354135, 2020). "Moreover, pharmacological inhibition of MM cells using the nonselective USP14 inhibitor b-AP15 induced the downregulation of cyclin B1 as well as caspase-dependent apoptosis in human MM xenograft models, preventing tumor growth and prolonging survival." (PMID 35069211, 2021).
neurodegenerative disease (18 papers, 2015 to 2026). A disorder of the central nervous system characterized by gradual and progressive loss of neural tissue and neurologic function. "Dysregulation of the deubiquitinating enzyme Ubiquitin-specific peptidase 14 (USP14) is implicated in several neurodegenerative diseases, and IU1, an allosteric inhibitor, has shown neuroprotective effects by reducing protein aggregate toxicity." (PMID 41752099, 2026). "USP14 reduces the degradation of pathogenic proteins by the 26S proteasome and is implicated in various neurodegenerative diseases, including AD." (PMID 39562545, 2024). "There have been several UPS components implicated in neurodegenerative diseases, including the deubiquinating components USP14 and cAMP." (PMID 31200561, 2019). "Open Science Framework: Dataset: Does inactivation of USP14 enhance degradation of proteasomal substrates that are associated with neurodegenerative diseases?, doi10.17605/OSF.IO/7G3MJ (Ortunoet al., 2016)." (PMID 26998235, 2016). "USP14 is a ubiquitin-specific protease that is associated with the proteasome and plays important roles in cellular functions, viral infection, inflammatory responses, neurodegenerative diseases, and tumorigenesis." (PMID 39562545, 2024). "Consistent with results from USP14 overexpression and loss-of-function analyses, treatment with USP14 inhibitors promotes the degradation of a variety of proteotoxic proteins within cells, including those highly implicated in neurodegenerative diseases—such as tau, TDP-43, ATXN3, and PrPSC." (PMID 32726943, 2020). "Taken together, these observations suggest that USP14 plays a complex, dual role in neurodegenerative diseases, acting as both a potential therapeutic target and a protector of neuronal health, depending on the disease context." (PMID 39840724, 2025). "The effects of USP14 inhibition on aggregates, such as tau and huntingtin, in neurodegenerative diseases are controversial." (PMID 38780644, 2024). "The effectiveness of IU1-47 series compounds for the treatment of neurodegenerative diseases through targeting USP14 requires further investigation." (PMID 35069211, 2021). "Previous studies have reported findings regarding effects of USP14 overexpression or inhibition on degradation of aggregation-prone proteins in neurodegenerative diseases." (PMID 31703099, 2019). "Collectively, above limited but seminal studies suggest that interventions targeting other DUBs such as USP13 and USP14 could serve as a promising therapeutic strategy for neurodegenerative diseases, including PD and AD." (PMID 39840724, 2025). "USP14 inhibition activates the proteasome, removes tau oligomers, and promotes huntingtin aggregation, suggesting that it contributes to aggregate deposition in neurodegenerative diseases." (PMID 38780644, 2024). "Therefore, inhibition of USP14 has been proposed as a therapeutic strategy to enhance proteasome function in neurodegenerative diseases." (PMID 39562545, 2024). "In addition, USP14 has been considered a therapeutic target for the treatment of neurodegenerative diseases, and selective inhibitors of USP14 were developed in 2010." (PMID 36693850, 2023). "Therefore, both the toxicity and effectiveness of IU1-47 in the treatment of neurodegenerative diseases through targeting USP14 requires further investigation." (PMID 35069211, 2021). "USP14 and its inhibitors (as discussed in Section 3) have been reported to regulate several pathological targets, such as Tau, ATXN3, TDP-43, GFAP, and PrP that are highly implicated in neurodegenerative diseases." (PMID 34207520, 2021). "Given that many neurodegenerative diseases including ADRP are associated with protein toxicity, we believe that the modulation of USP14 could be a potential therapeutic strategy for the treatment of such diseases." (PMID 33053617, 2020). "We were interested in USP14 as a potential drug target for neurodegenerative diseases." (PMID 31703099, 2019).
neurodegenerative disease (continued). "Thus, inhibition of USP14 was proposed as a therapeutic strategy to enhance proteasomal function in neurodegenerative diseases in which these proteins accumulate." (PMID 26998235, 2016). "The involvement of other DUBs such as USP14, USP15, and USP33 further complicates the landscape of neurodegenerative diseases." (PMID 39840724, 2025). "In agreement with this, a highly selective inhibitor of USP14, IU1, (IC50 of Ub-AMC hydrolysis by proteasome-bound USP14 is 4.7 ± 0.7 μM), enhanced the destruction of several important proteasome substrates (Tau, TDP-43) involved in the development of neurodegenerative diseases." (PMID 26295307, 2015). "We were interested in the effect of USP14 inhibition on reducing neurodegenerative disease proteins such as α-synuclein, TDP-43, and tau, but neither USP14 inhibitors nor USP14 C114A showed consistent and significant effects on these proteins in HEK293T cells." (PMID 31703099, 2019).
neurological diseases (6 papers, 2012 to 2023). "In this study, we identified and characterized an N-ethyl-N-nitrosourea (ENU) induced mutation in Usp14 (nmf375) that leads to adult-onset neurological disease." (PMID 24358326, 2013). "Backcrossing the nmf375 and axJ mutations onto C57 and BALB/c, respectively, demonstrated that a genetic modifier(s) can alter the severity of neurological disease caused by USP14 deficiency." (PMID 24358326, 2013). "USP14 inhibition promotes the clearance of neuropathic substrates by increasing proteasome activity, which would be among the underlying mechanisms for treating the neurological disorders." (PMID 34207520, 2021). "More is yet to be discovered about USP14 and its diverse roles in other neurological diseases such as AD, but investigation of the therapeutic value and inhibitors of USP14 is already ongoing and potentially holds great promise for the future." (PMID 36831318, 2023). "In contrast, in immortalized cell lines, inhibition of USP14 appears to accelerate the degradation of proteins known to aggregate in neurological diseases." (PMID 25575639, 2015). "We have recently reported that Usp14 is required for the stable expression of neurological disease-related proteins, such as tau and ataxin-3, in mouse embryonic fibroblasts." (PMID 23144711, 2012). "However, genetic ablation of tau did not alter any of the neurological deficits in the Usp14-deficient mice, demonstrating that increased levels of phosphorylated tau do not necessarily lead to neurological disease." (PMID 23144711, 2012). "The lack of severe neurological disease within the first 4-6 weeks of life suggested that nmf375 mutants were able to regulate ubiquitin levels even in the absence of USP14." (PMID 24358326, 2013).
infection (4 papers, 2012 to 2023). The state of being infected such as from the introduction of a foreign agent such as serum, vaccine, antigenic substance or organism. "On the other hand, infection of mice with a Usp14-encoding adenovirus via the tail vain substantially enhanced triglyceride content in the liver and elevated plasma triglyceride levels." (PMID 36834633, 2023). "Our work demonstrates for the first time that a cellular DUB, the proteasome-associated USP14, is required for optimal MNV-1 infection of murine macrophages." (PMID 22792064, 2012). "The western blotting analysis of the probe-reacted deubiquitinases was used as a validation, where the level of USP14, USP15, OTUD6B and USP47 was diminished during infection with Y. enterocolitica at 18 hpi." (PMID 37026055, 2023). "In response to infection, in male mice, the TACC2, BUB1B, ATP5MC3, and MYO1E, and in female mice, the CAP1, MRPL2, COX5A, KLHL21, PDIA6, TSPO, and USP14 had direct interaction with TP-53." (PMID 35844510, 2022). "Although decreased viral titers following USP14 knockdown were also observed in RAW cells 8 hours post-infection by plaque assay, this was not statistically significant (data not shown)." (PMID 22792064, 2012).
metabolic disease (3 papers, 2018 to 2024). A congenital disorder (due to inherited enzyme abnormality) or acquired (due to failure of a metabolically important organ) disorder resulting from an abnormal metabolic process. "Knockdown USP14 in obese mice showed reduced glucose, and ER stress suggested USP14 has potential targets for metabolic disease therapeutics." (PMID 38673794, 2024). "In conclusion, the results of our present study demonstrate that USP14 plays an important role in hepatosteatosis through FASN stabilization and represents a therapeutic target in fatty liver and related metabolic disorders." (PMID 30425250, 2018). "With respect to the modulation of key molecules for metabolic diseases, such as FASN and CBP, USP14 might not only disassemble the ubiquitin chain on target proteins, but might also affect the incorporation of the targets into the proteasome." (PMID 36834633, 2023).
adenocarcinoma (1 paper, 2013). A common cancer characterized by the presence of malignant glandular cells. "It was found that USP14 expression was upregulated in NSCLC cells, especially in adenocarcinoma cells." (PMID 23702845, 2013).
cardiovascular diseases (1 paper, 2025). "USP14's role in cardiovascular diseases is also gaining attention." (PMID 40988122, 2025).
USP14 also shares sentences with these, for which no sentence is quoted: esophageal squamous cell carcinoma (5 papers); intrahepatic cholangiocarcinoma (3); Waldenstrom macroglobulinemia (3); chronic myeloid leukaemia (2); diabetes (2); neuropathies (2); steatosis (2); triple-negative breast carcinoma (2); anaplastic thyroid cancer (1); anemia (1); aneurysmal bone cyst (1); Angelman syndrome (1); behavioral disorders (1); bilirubin encephalopathy (1); cerebellar ataxia (1); Cerebral ischemia (1); Cirrhosis (1); colorectal (1); dementia disease (1); diffuse large B-cell lymphoma (1); Ewing sarcoma (1); fibrosis (1); hematological malignancies (1); Hyperinsulinemia (1); lung squamous cell carcinoma (1); mantle cell lymphoma (1); mesenchymal tumors (1); metastasis (1); monocytic leukemia (1); myocardial infarction (1).
A further 16 diseases each share a sentence with USP14 in 1 paper.